LIG4 (DNA ligase 4)
Diseases named in the same sentence as LIG4 in open-access papers (continued):
Sharing a sentence is not in itself a finding about the gene and the disease.
tumor (62 papers, 1988 to 2025). "Low nuclear LIG4 was significantly associated with larger residual tumours (p = 0.006), poor response to platinum-based chemotherapy (p = 0.049), poor PFS (p = 0.041) and poor OS (p = 0.016) compared with high nuclear LIG4 expressing tumours." (PMID 34373746, 2021). "It is likely that LIG4 deficiency observed in the current study may reflect NHEJ defective tumours." (PMID 34373746, 2021). "In tumor cells, the correct localization of LIG4 is critical for maintaining genomic integrity, especially following exposure to DNA-damaging agents such as radiation." (PMID 40744919, 2025). "This creates an opportunity to explore the regulatory factors that control LIG4 localization and activity in tumor cells." (PMID 40744919, 2025). "Low nuclear LIG4 was seen in 260/374 (69.5%) tumours and 114/374 (30.5%) of the tumours had high LIG4 nuclear expression." (PMID 34373746, 2021). "Among these HuR post-transcriptionally regulated mRNAs, LIG4 was the most striking one due to its potent anti-tumor effect." (PMID 27303922, 2016). "TSA mediated H3K9Ac is reversible within about 2 h of drug removal, irrespectively of treatment duration between 2-8 h, in exponentially growing and serum deprived Lig4-/- MEFs, as well as in the human tumor cell line, M059K." (PMID 22908892, 2012). "In all tumour cell lines, decreased LIG4 expression was observed." (PMID 36142793, 2022). "A total of 374 tumours were suitable for analysis of LIG4 nuclear expression." (PMID 34373746, 2021). "ATM is a known gene active in radiation-induced DNA damage repair, but LIG4 and RNF8 are less well known genes in radiation response in HNSCC, although their role in DNA repair has been well studied in other tumor models." (PMID 40768535, 2025). "This analysis revealed significant upregulation of five genes, (XRCC6, XRCC4, PRKDC, XRCC4, and PAXX) and downregulation of two (LIG4 and NHEJ1) NHEJ pathway genes, in tumor tissues compared to the normal tissues." (PMID 33195430, 2020). "Furthermore, expression of DNA repair genes LIG4 and RAD9B increased significantly at mRNA level in tumor xenografts." (PMID 32074079, 2020). "Consistent with the Oncomine analysis, comparison of all available normal (n = 41) and tumor tissues (n = 469) revealed overexpression of XRCC6, XRCC5, PRKDC, XRCC4, and PAXX in tumors compared to normal tissues, while LIG4 and NHEJ1 displayed lower expression in the tumor tissues." (PMID 33195430, 2020). "Further analysis determined that PMS2 (MMR) and LIG4 (NHEJ), essential components of their respective pathways, were downregulated across multiple cell lines after chronic and acute hypoxic exposure, providing potential targets for re-sensitisation of hypoxic tumour cells to DNA damaging therapies." (PMID 33986995, 2021). "However, analysis of 41 paired normal and tumor tissues revealed significant overexpression of only XRCC5, PRKDC, and PAXX genes in tumor tissues compared to the normal colon (respectively), while LIG4 and NHEJ1 still displayed reduced expression (respectively)." (PMID 33195430, 2020). "In contrast, significantly lower mRNA expression in tumor samples with high CIN70 score was observed for SMC1 (**), ERCC1 (***) and LIG4 (****), and a non-significant for XRCC4 (n.s.)and BOD1L1 (n.s.)." (PMID 33801877, 2021).
infection (13 papers, 2011 to 2025). The state of being infected such as from the introduction of a foreign agent such as serum, vaccine, antigenic substance or organism. "The remaining patients (P11–P15) have not received HCT, but continue to survive; all receive IVIG and oral co-trimoxazole to prevent infection (standard treatments after a diagnosis of LIG4 deficiency)." (PMID 34630384, 2021). "At the same time, upregulation of key components that catalyze end-processing and ligation, namely, RAD50, ARTEMIS, XRCC4, and LIG4, was observed upon infection." (PMID 33339161, 2020). "The identification of LIG4 and DAXX under mock but not infection conditions prevented calculation of log2 fold change and associated P values but supported that these proteins are degraded by Ad5 infection." (PMID 34463575, 2021).
genetic diseases (4 papers, 2017 to 2024). "LIG4 dificiency is a very rare genetic disease that is caused by mutations in the LIG4 gene (13q22-q34)." (PMID 36221079, 2022).
neurological disease (3 papers, 2013 to 2022). "Mutations in the human orthologs of some genes carrying NSph-T-DMR, such as LIG4 and NFIA, are associated with neurological disorders." (PMID 23387509, 2013).
LIG4 also shares sentences with these, for which no sentence is quoted: developmental delay (6 papers); cervical cancer (4); hepatocellular carcinoma (4); Myelodysplasia (4); Pancytopenia (4); Bloom syndrome (3); COVID-19 (3); esophageal cancer (3); liver cancer (3); Obesity (3); sarcoma (3); anemia (2); aplastic anemia (2); Ataxia oculomotor apraxia-1 (2); combined immunodeficiency (2); DiGeorge syndrome (2); eosinophilia (2); growth failure (2); lupus (2); neurodegenerative disease (2); pulmonary fibrosis (2); skin cancer (2); achondroplasia (1); adenocarcinoma (1); adenoma (1); adenovirus infection (1); Aicardi–Goutières syndrome (1); alopecia (1); AMeD syndrome (1); anaplastic thyroid cancer (1).
A further 77 diseases each share a sentence with LIG4 in 1 paper.